CRACR2B (calcium release activated channel regulator 2B)
Description:
Plays a role in store-operated Ca(2+) entry (SOCE).
Synonyms: EFCAB4A; MGC45840
Tractability: No criterion of Open Targets' tractability assessment is met for any kind of drug.
Gene: Protein-coding gene on chromosome 11 (826,144 to 831,993, forward strand). Ensembl gene ENSG00000177685.
Gene Ontology:
Molecular function: protein binding; calcium ion binding
Biological process: store-operated calcium entry
Genetic constraint (gnomAD): Loss-of-function variants: 48 observed, 35.34 expected, observed/expected ratio (o/e) 1.36, 90% interval 1.08 to 1.72. The synonymous counts are far from expectation, so gnomAD's model fits this gene poorly and the ratio says little. Missense variants: 571 observed, 419.82 expected, observed/expected ratio (o/e) 1.36, 90% interval 1.27 to 1.46. Synonymous variants: 241 observed, 186.06 expected, observed/expected ratio (o/e) 1.3, 90% interval 1.16 to 1.44.
Homologues: Orthologues: chimpanzee CRACR2B (99% identical), macaque CRACR2B (94% identical), dog CRACR2B (80% identical), pig CRACR2B (80% identical), rat Cracr2b (76% identical), mouse Cracr2b (76% identical), guinea pig CRACR2B (73% identical), tropical clawed frog cracr2b (40% identical), zebrafish cracr2b (36% identical). Paralogues in human: CRACR2A (35% identical).
Diseases named in the same sentence as CRACR2B in open-access papers:
CRACR2B is named in the same sentence as 5 diseases in open-access papers, as found by Europe PMC text mining. Sharing a sentence is not in itself a finding about the gene and the disease. The quoted sentences say what the papers report.
Obesity (1 paper, 2018). Accumulation of substantial excess body fat. "Contrary to CRACR2B, evidence for a direct association between IRF7 and obesity have been shown with IRF7 knockout mouse being protected from gain weight after high-fat diet exposure." (PMID 30452450, 2018).
rheumatoid arthritis (1 paper, 2023). A chronic, systemic autoimmune disorder characterized by inflammation in the synovial membranes and articular surfaces. "The KEGG analysis showed that the downregulated genes at day 3 Cracr2b, Nr4a1, Fos, Jun, Vegfa were involved in the MAPK signalling pathway, Nr4a1, Fos, Jun were involved in the relaxin signalling pathway, chemical carcinogenesis-receptor activation, and rheumatoid arthritis." (PMID 36445632, 2023).
Stillbirth (1 paper, 2024). Death of the fetus in utero after at least 22 weeks of gestation. "Genes TBC1D17 associated with sire calving ease, and CRACR2B associated with sire stillbirth, were also identified (P < 0.05)." (PMID 38711039, 2024).
CRACR2B also shares sentences with these, for which no sentence is quoted: neuromuscular disease (1 paper); overnutrition (1).